HOXA11-AS (HOXA11 antisense RNA)
Synonyms: HOXA11-AS1; HOXA11S; HOXA-AS5; NCRNA00076; LncHOXA11; HOXA11AS
Gene: Long non-coding RNA gene on chromosome 7 (27,184,507 to 27,189,298, forward strand). Ensembl gene ENSG00000240990.
Gene Ontology:
Biological process: negative regulation of gene expression
Diseases named in the same sentence as HOXA11-AS in open-access papers:
HOXA11-AS is named in the same sentence as 6 diseases in open-access papers, as found by Europe PMC text mining. Sharing a sentence is not in itself a finding about the gene and the disease. The quoted sentences say what the papers report.
breast carcinoma (1 paper, 2020). "According to the literature, HOXA11AS is upregulated in breast cancer cell lines (e.g., SNHG15) and stimulates breast cancer invasion and metastasis by regulating the epithelial-mesenchymal transition." (PMID 31319040, 2020).
gastric cancer (1 paper, 2022). A primary or metastatic malignant neoplasm involving the stomach. "The results of our study demonstrated that the five-lncRNAs PART1, UCA1, DIRC3, HOTAIR, and HOXA11AS require more investigation to be confirmed as diagnostic biomarkers in gastric cancer." (PMID 35949302, 2022).
head and neck cancer (1 paper, 2022). A primary or metastatic malignant neoplasm affecting the head and neck. "HOXA11AS is one of the 16 most dysregulated lncRNAs in head and neck cancer and has attracted attention as a therapeutic target." (PMID 36142607, 2022).
ovarian carcinoma (1 paper, 2021). A malignant neoplasm originating from the surface ovarian epithelium. "It was suggested that the regulation of some long non-coding RNAs, such as HOTAIR, UCA1, HOXA11AS, etc., through RNAi techniques or CRISPR/Cas-9 was thought to be a promising therapy for ovarian cancer." (PMID 34765618, 2021).
tumor (2 papers, 2017 to 2022). "Our bioinformatics data illustrated that lncRNAs PART1, UCA1, DIRC3, HOTAIR, and HOXA11AS have more differential expression in the tumor tissues versus normal counterpart margins." (PMID 35949302, 2022).
cancer (1 paper, 2020). A tumor composed of atypical neoplastic, often pleomorphic cells that invade other tissues. "Only HOXA11as is indicated as an important lncRNA in progression and metastasis of a number of different cancers by regulating proteins and miRNAs crucial in cellular processes such as cell cycle, apoptosis, epithelial-to-mesenchymal transition (EMT) process, invasion and metastasis." (PMID 32947877, 2020).